MGMT (O-6-methylguanine-DNA methyltransferase)
Diseases named in the same sentence as MGMT in open-access papers (continued):
Sharing a sentence is not in itself a finding about the gene and the disease.
glioblastoma (continued). "The observed association between glioblastoma shape complexity and MGMT promoter methylation is also interesting and could be of relevance to the field of radiogenomics." (PMID 39531176, 2024). "Survival varies considerably by grade, histology, biomarkers, and genetic alterations such as IDH mutations and MGMT promoter methylation, and treatment, but is poor for some grades and histologies, with many patients with glioblastoma surviving less than a year from diagnosis." (PMID 38571509, 2024). "Methylation of the MGMT promoter or inactivating mutations have been associated with several cancer types, including colorectal cancer, lung cancer, prostate cancer, lymphoma, glioblastoma, and astrocytoma." (PMID 37019990, 2023). "Patients with objective responses in this study had tumors that did not universally harbor the prognostically favorable mutation in IDH1 and had both MGMT methylated and unmethylated tumors, representing the group of glioblastomas that desperately need efficacious therapies." (PMID 37188783, 2023). "Loss of enzymatic activity of MGMT is correlated with prolonged survival of patients affected by glioblastoma that received temozolomide treatment; in fact this mechanism is a valid help to induce, by using temozolomide, DNA damage in glioblastoma with consequent cellular death." (PMID 37371106, 2023). "More recently, radiomics has been used to identify brain abscess from cystic gliomas, predict the molecular subtypes of HGGs (such as IDH and MGMT status), assess the antiangiogenic treatment response of recurrent glioblastomas (GBMs), and stratify the risk of patients with GBMs." (PMID 35386727, 2022). "A better progression free survival was seen in glioblastoma patients carrying rs1625649 “AA” genotypes which was in turn associated with lower MGMT expression and was also shown to reduce the expression of MGMT as a part of investigated promoter haplotypes." (PMID 34711928, 2022). "MGMT is a DNA repair enzyme, and it counteracts the damage in the DNA caused by the alkylating agent temozolomide, the standard chemotherapy used for glioblastoma." (PMID 36428772, 2022). "One study showed that glioblastoma patients with the dual inactivation of MGMT, by loss of the long arm of chromosome 10 and the hypermethylation of the MGMT promoter, have longer progression-free survival and overall survival, and respond well to temozolomide therapy." (PMID 35806478, 2022). "Besides IDH1/2 mutations, the methylation status of the MGMT gene promoter is commonly used in the clinical diagnostic of glioblastoma as a predictive marker of sensitivity to TMZ." (PMID 35884887, 2022). "In glioblastoma, hypermethylation of MGMT is associated with response to temozolamide." (PMID 34208598, 2021). "Relationship between IDH1 mutation and MGMT promoter methylation in glioblastoma patients." (PMID 34257620, 2021). "The aim of this study is to investigate the relationship between isocitrate dehydrogenase-1 (IDH1) mutation and O6-methylguanine-DNA methyltransferase (MGMT) promoter methylation with recurrence-free interval in glioblastoma patients treated with chemoradiotherapies." (PMID 34257620, 2021). "MGMT is involved in DNA repair and its expression is associated with drug resistance including temozolamide, the most frequent first-line chemotherapy used in a context of glioblastoma." (PMID 33915852, 2021). "Interestingly, inhibition of these ion channels has been reported to render MGMT promoter-methylated glioblastoma cells more susceptible for a therapy with temozolomide." (PMID 33673490, 2021).
glioblastoma (continued). "Among the findings of the paper was the impact of the chemotherapy temozolomide (TMZ) on low-grade gliomas; in six patients, tumor samples acquired after treatment with TMZ showed hypermutation and progression to high-grade glioblastoma in the context of MGMT silencing and loss of mismatch repair." (PMID 34252935, 2021). "MGMT-promoter methylation is associated with favorable outcome in glioblastoma." (PMID 33663593, 2021). "In addition to IDH mutations and MGMT hypermethylation, there are a number of other genetic biomarkers that are commonly altered in glioblastoma that have a less clear effect on treatment and prognosis." (PMID 32678261, 2020). "Temozolomide resistance in glioblastoma is associated with MGMT overexpression." (PMID 31053733, 2019). "However, glioblastoma is genetically a highly heterogeneous cancer, and several targets have been implicated in chemoresistance, including MGMT, isocitrate dehydrogenase (IDH) 1/2, and epidermal growth factor receptor." (PMID 30717309, 2019). "Temozolomide (TMZ) resistance in glioblastomas (GBM) is associated with increased MGMT expression." (PMID 30054476, 2018). "Interestingly, LA has been shown to cause hypermethylation of the MGMT promoter, resulting in decreased MGMT proteins in glioblastoma." (PMID 29925764, 2018). "On the contrary, in treatment-naive glioblastoma, reduced ADC values before antiangiogenic therapy correlated with better outcomes, possibly due to an association with MGMT methylation, highlighting the genetic differences of untreated and recurrent glioblastomas." (PMID 29403420, 2017). "The MGMT gene, located in chromosome band 10q26, has previously been associated with several cancer types where its epigenetic silencing has been described, such as glioblastoma, colorectal cancer and gastric cancer." (PMID 27776349, 2017). "A recent report has found that O6-methylguanine-DNA methyltransferase (MGMT) gene promoter hypermethylation is associated with response of glioblastoma to temozolomide therapy and may be a key factor determining a response to this agent." (PMID 27721667, 2016). "Moreover, the combination of two biomarkers (IDH1 mutation and MGMT methylation status) outperforms either IDH1 mutations or MGMT methylation alone in predicting survival of glioblastoma patients." (PMID 27379174, 2016). "Therefore, glioblastoma tumors expressing MGMT have been implicated as a major intrinsic mechanism of resistance to TMZ, although a different mechanism independent of MGMT has been reported." (PMID 26546412, 2015). "MGMT encodes a repair protein which removes alkyl groups from the O6-position of guanine residues and its promoter methylation has been described as a biomarker in several studies, especially for glioblastoma and colorectal cancer." (PMID 26106605, 2015). "Therefore, methylated MGMT promoter alone is less likely to be associated with underlying genetic or epigenetic alterations that molecularly define a more favorable glioblastoma subtype." (PMID 24454798, 2014).
glioblastoma (continued). "Thus, understanding the mechanism underlying the heterogeneity of MGMT expression can fundamentally impact clinical care of glioblastoma patients." (PMID 24994119, 2014). "MGMT promoter methylation is associated with a favorable outcome and predicts a benefit from alkylating agent chemotherapy in patients with newly diagnosed glioblastoma." (PMID 23704990, 2013). "Some investigators had suggested that the epigenetic silencing of a DNA repair enzyme named O-6-methylguanine-DNA methyltransferase (MGMT) by promoter methylation was associated with good prognosis for patients with glioblastoma treated with alkylating agents such as TMZ." (PMID 22530121, 2012). "Hypermethylation in the promoter region of the MGMT gene encoding the DNA repair protein O6-methylguanine-DNA methyltransferase is among the most important prognostic factors for patients with glioblastoma and predicts response to treatment with alkylating agents like temozolomide." (PMID 22428052, 2012). "Epigenetic silencing of the MGMT gene by promoter methylation is associated with loss of MGMT expression, diminished DNA-repair activity and longer overall survival in patients with glioblastoma who, in addition to radiotherapy, received alkylating chemotherapy with carmustine or temozolomide." (PMID 20167086, 2010). "Importantly, MGMT promoter methylation has been associated with response of glioblastomas to alkylating chemotherapy using nitrosourea compounds, temozolomide, or a combination of both." (PMID 19333441, 2009). "However the benefit from temozolomide treatment in glioblastoma is strongly associated with MGMT promoter methylation." (PMID 19114005, 2008). "MGMT promoter methylation status (hypermethylation) is one of the strongest prognostic and predictive biomarkers in glioblastoma (GBM) and is associated with a more favorable response to alkylating chemotherapies such as Temozolomide (TMZ)." (PMID 40250264, 2025). "Additionally, promoter hypermethylation of MGMT, encoding O6-methylguanine-DNA methyltransferase, is used as a biomarker of MGMT silencing, which correlates with reduced responsiveness to temozolomide in glioblastoma." (PMID 40427586, 2025). "Therefore, we hypothesized that MGMT promoter methylation in glioblastoma may cause subtle changes in tumor cell morphology through interactions with other genes, which can be captured by the neural network model to obtain corresponding predictions." (PMID 38385046, 2024). "Recent findings from our research indicate that the methylation of MGMT enhancer regions plays a role in regulating MGMT expression and is associated with various clinical parameters in patients with glioblastoma (GBM)." (PMID 38791122, 2024). "For example, chemoresistance to the DNA-alkylating agent temozolomide occurs in >90% of recurrent glioblastoma multiforme (GBM), often through increased expression of MGMT which encodes an alkyltransferase capable of repairing the DNA damage." (PMID 36672409, 2023). "Interestingly, even in MGMT-deficient glioblastoma, TMZ resistance may still arise due to the loss of mismatch repair (MMR) pathway in tumor cells." (PMID 38239396, 2023). "An interesting question that arises in this context is whether epigenetic downregulation of MGMT already occurs in glioblastoma progenitor cells, which would be causally related to malignant transformation since O6-methylguanine is a highly potent premutagenic and precarcinogenic lesion." (PMID 38068493, 2023).
glioblastoma (continued). "In addition, DNA methylation biomarkers are also useful for predicting cancer treatment response; for example, tumor MGMT (gene important in DNA repair) promotor hypermethylation is associated with good response to alkylating drugs and used in clinical testing in glioblastomas." (PMID 35892331, 2022). "In the present analysis, we evaluated the impact of MGMT promoter methylation as well as IDH1 mutation status on recurrence-free interval (the period from beginning of adjuvant therapy after surgical resection to the possible first date of recurrence) in patients with glioblastoma." (PMID 34257620, 2021). "Similarly, epigenetic silencing of the DNA repair enzyme MGMT by promoter hypermethylation is present in a minority of cases of glioblastoma (~ 35%) and is associated with both improved survival and favorable response to the first line DNA-alkylating chemotherapy agent temozolomide." (PMID 32678261, 2020). "Furthermore, despite increasing the efficacy of chemotherapeutic agents such as TMZ, HDAC inhibitors may potentiate the evolution of acquired TMZ resistance linked to MGMT upregulation in glioblastoma xenografts." (PMID 29486795, 2018). "The methylation status of oxygen 6-methylguanine-DNA methyltransferase (MGMT) promoter has been associated with treatment response in glioblastoma(GBM)." (PMID 29467012, 2018). "The methylation level of the promoter of MGMT (O6-methylguanine-DNA methyltransferase), a radiation-induced gene that encodes a DNA repair enzyme responsible for removing alkyl groups from guanine, was identified as a predictive epigenetic biomarker in glioblastoma." (PMID 29439529, 2018). "In the present study, we showed that MGMT promoter methylation status was significantly associated with an increased risk of breast and gynecologic cancers, which is consistent with previous studies in head and neck squamous cell carcinoma, lung cancer, glioblastoma, and esophageal cancer." (PMID 28986566, 2017). "As hypothesized the MGMT promoter methylation degree of the analyzed glioblastoma samples was significantly correlated with the genotypes of the MGMT C-56 T polymorphism (Wilcoxon test, p-value = 0.02), showing a higher methylation level in patients with the T allele." (PMID 24380367, 2013). "Although epigenetic silencing of the MGMT gene promoter has been associated with prolonged survival in glioblastoma patients, there is much controversy about its use as a prognostic marker for the response of patients with newly diagnosed glioblastoma to temozolomide." (PMID 23245659, 2012). "Epigenetic silencing of the MGMT gene by promoter methylation is associated with loss of MGMT expression, diminished DNA-repair activity and longer overall survival in patients with glioblastoma (GBM) who, in addition to radiotherapy, received alkylating chemotherapy with temozolomide." (PMID 20167086, 2010). "Surgical extent, treatment intensity, and MGMT methylation remain key determinants of survival in older patients with glioblastoma." (PMID 42240773, 2026). "Consistent with the results of the current study, a prior study revealed that hypermethylation-induced MGMT epigenetic silencing is present in about 40% of primary glioblastomas." (PMID 41596413, 2026). "CONCLUSION: CRISPR-Cas13-mediated targeting of MGMT mRNA is an effective strategy for overcoming TMZ resistance in in vitro glioblastoma models." (PMID 41817895, 2026). "CONCLUSIONS: Maximal resection significantly improves survival in glioblastoma patients aged ≥ 75 years, particularly those with MGMT-methylated tumors, and should be considered even in selected patients aged ≥ 80 years." (PMID 41661370, 2026). "Overall, this meta-analysis reinforces the importance of Gross Total Resection and MGMT promoter methylation as pivotal predictors of survival in recurrent glioblastoma." (PMID 41530365, 2026).
glioblastoma (continued). "On the other hand, while the prognostic relevance of O6-methylguanine-DNA-methyltransferase (MGMT) promoter methylation is established in glioblastoma." (PMID 41680847, 2026). "MGMT promoter methylation has been widely accepted as a predictive biomarker for prognosis in glioblastoma patients undergoing treatment with alkylating agents such as temozolomide." (PMID 41530365, 2026). "Given the potential predictive power of this biomarker, routine testing of MGMT promoter methylation in recurrent glioblastoma is warranted to guide therapeutic decision-making." (PMID 41530365, 2026). "The pooled multivariate hazard ratios for GTR (HR = 0.70, 95% CI: 0.53–0.93) and methylated MGMT promoter status (HR = 0.45, 95% CI: 0.27–0.76) highlight their critical roles in the management of recurrent glioblastoma." (PMID 41530365, 2026). "Methylation of the MGMT promoter is a well-established biomarker for predicting the efficacy of alkylating agents such as temozolomide in glioblastoma." (PMID 41530365, 2026). "A widely discussed use-case is the prediction of O6-methylguanine-DNA methyltransferase (MGMT) promoter methylation status, which is a key indicator of response to temozolomide chemotherapy in glioblastoma." (PMID 39753730, 2025). "In glioblastoma, MGMT promoter methylation significantly improves survival outcomes in TERTp-mutant tumors." (PMID 40862791, 2025). "As such, glioblastomas usually undergo testing for MGMT promoter hypermethylation, and the results are used, with other relevant patient data, to stratify cases into those receiving temozolomide or alternative treatments." (PMID 39066464, 2025). "Among glioblastoma samples with unmethylated MGMT promoter, significantly higher methylation levels were found in samples with high Ki-67 index at CpG 27 in enhancer B (p = 0.023), and CpG 13, 26, and 27 (p ≤ 0.029) in enhancer E." (PMID 40244270, 2025). "The primary benefit of temozolomide is seen in patients with MGMT methylated glioblastomas where the median survival is increased from 15 to 24 months." (PMID 40225909, 2025). "We performed a multicentric analysis aiming to validate recently proposed sex‐specific cutoff values using a homogeneous cohort of newly diagnosed MGMT promoter methylated glioblastoma patients; we included a balanced control cohort for comparison." (PMID 40260649, 2025). "Accurate pre-operative determination of MGMT status is a critical prognostic and predictive biomarker, as methylation sensitizes glioblastomas to temozolomide (TMZ) chemotherapy." (PMID 41295120, 2025). "We also pinpointed eight quantitative features that exhibited a significant difference before and after radiotherapy in patients with MGMT-unmethylated glioblastoma." (PMID 40881875, 2025). "Determination of the safety and tolerability of combinational treatment in newly diagnosed MGMT promoter methylated and unmethylated glioblastoma." (PMID 41208963, 2025). "Mitochondria‐targeted temozolomide (mtTmz) using peptide‐based delivery vector has been shown to overcome direct DNA repair and resistance by O6‐methylgunaine DNA methyltransferase (MGMT) in glioblastoma (GBM) cells." (PMID 39969500, 2025). "Recent studies have observed that HIF-1 inhibition can reduce MGMT levels in glioblastoma stem cells." (PMID 40002588, 2025). "These insights underscore the prognostic importance of EGFR and MGMT status in shaping glioblastoma treatment outcomes and recurrence dynamics." (PMID 40722305, 2025). "The HOXB9 gene shows elevated expression in patients with high-grade glioblastoma (GBM) and is associated with multiple drug-resistant mechanisms, including MGMT and P-gp." (PMID 41515958, 2025). "This study aimed to assess DNA methylation levels in intergenic and intragenic MGMT enhancers to investigate their relationship with MGMT promoter methylation, MGMT protein expression, and clinical and demographic characteristics in glioblastoma." (PMID 40244270, 2025).